MTOR (mechanistic target of rapamycin kinase)
Diseases named in the same sentence as MTOR in open-access papers (continued):
Sharing a sentence is not in itself a finding about the gene and the disease.
Hyperglycemia (continued). "Conversely, hyperglycemia has been linked to enhanced tumorigenesis and worse cancer outcomes through several pathways, including its role as an energy source for rapidly proliferating tumor cells, supporting the Warburg effect, and activating pro-survival pathways such as Akt and mTOR signaling." (PMID 41585801, 2025). "Interestingly, as hypothesised by Laplante & Sabatini and others, hyperactivation as well as hypoactivation of mTOR is thought to be the cause for hyperglycemia." (PMID 35804402, 2022). "Therefore, downregulation of mTOR activity by various factors associated with prolonged hyperglycemia may be responsible for the autophagy-induced neuronal cell death in the DR." (PMID 33637094, 2021). "In xenografts, PAC-XL outperformed cetuximab, BGT226 and alpelisib, including complete regressions, while reducing hyperglycemia and weight loss caused by systemic PI3K/mTOR inhibition." (PMID 42183362, 2026). "Critically, functional linkage is demonstrated by the ability of BMAL1 overexpression to protect cardiomyocytes from hyperglycemia-induced damage; it achieves this by blocking the mTOR pathway, thereby reversing hyperglycemia-induced autophagy suppression." (PMID 41234362, 2025). "In other words, the overactivation of mTOR requires suppression to restore autophagy during metabolic stress (e.g., hyperglycemia), whereas moderate mTOR activation can initiate protective autophagy during cellular differentiation or proteostasis imbalance." (PMID 41155562, 2025). "Specifically, we observed that hyperglycemia significantly promotes mTOR phosphorylation, which subsequently suppresses autophagic activity and impairs autophagic flux." (PMID 41300463, 2025). "Further, defective ERCC1-XPF causes increased GLUT1 and GLUT3-mediated hepatocyte glucose uptake, and the resulting hyperglycemia activates pro-inflammatory responses via mTOR." (PMID 40065360, 2025). "Hyperglycemia inhibits the PI3K/Akt/mTOR pathway, suppressing T cell proliferation and differentiation, thereby weakening immune responses and increasing susceptibility to infections." (PMID 40385356, 2025). "Upstream, TXNIP links hyperglycemia to oxidative stress and mTOR/EMT activation; knockdown reduces ROS and renal injury and associates with mTOR activity in human biopsies." (PMID 41009556, 2025). "Under conditions of hyperglycemia/hyperinsulinemia, PKCζ is activated and drives pancreatic β‐cell proliferation via the mammalian target of rapamycin (mTOR)–cyclin D2 axis, thus helping to preserve insulin secretory capacity." (PMID 41244006, 2025). "Hyperinsulinemia and hyperglycaemia can enhance tumour cell proliferation by stimulating the phosphatidylinositol-3-kinase (PI3K) signalling cascade that stimulates the mammalian target of rapamycin (mTOR) through the protein kinase B (Akt)." (PMID 41002741, 2025). "Other challenges of PI3K/Akt/mTOR-targeted therapy include drug-related adverse events and/or direct-drug toxicity, such as hyperglycemia, diarrhea, nausea, vomiting, cutaneous reactions, hypertension, hepatotoxic effects, and neuropsychiatric problems." (PMID 38542151, 2024). "Clinical trials have reported a 13–50% prevalence of new-onset diabetes and hyperglycemia in people taking mTOR inhibitors." (PMID 39199594, 2024). "Clinical trials have reported high rates of hyperglycemia in patients treated with AKT/PI3K/mTOR inhibitors, necessitating careful monitoring and management of blood sugar levels in these patients when they are undergoing surgery." (PMID 39199594, 2024). "In agreement with our results, mTOR has been demonstrated previously to be involved in hyperglycemia-induced renal diseases." (PMID 39261960, 2024). "Studies performed on animals reported that metformin and rapamycin reduced inflammation, hyperlipidemia and hyperglycemia, and induced autophagy by blocking mTOR." (PMID 39200267, 2024). "mTOR inhibitors‐induced hyperglycemia is mediated by the development of IR and impairment of insulin secretion." (PMID 39676616, 2024).
Hyperglycemia (continued). "More than that, it is considered the first line of treatment against PI3K/AKT/mTOR inhibitors that induce hyperglycemia." (PMID 39200267, 2024). "mTOR hyperactivation disturbs glucose metabolism, leading to hyperglycemia and further to IR, with a higher incidence in the Western population." (PMID 39200267, 2024). "Identifying the downstream effectors of mTOR that mediate bone metabolism in hyperglycemia is also a key priority." (PMID 37298150, 2023). "To determine the generalizability to other cell populations directly exposed to hyperglycemia and vulnerable to diabetic complications, we examined MTOR regulation in human vascular endothelial cells." (PMID 36633903, 2023). "In vitro, hyperglycemia increased the expression of inducible costimulatory (ICOS) in Tfh cells via the mechanistic target of the rapamycin (mTOR) signaling pathway." (PMID 37139075, 2023). "mTOR activation is necessary for the tube formation of bone marrow-derived endothelial progenitor cells (EPCs) and human umbilical vein endothelial cells (HUVECs), which can be inhibited in hyperglycemia through mTOR suppression." (PMID 37298150, 2023). "We have thoroughly reviewed the current knowledge regarding the involvement of mTOR signaling in bone metabolism in hyperglycemia, including its effects on bone formation, bone resorption, inflammatory responses and bone vascularity." (PMID 37298150, 2023). "In this regard, AMPK/ACC/mTOR pathway helps anthocyanin-rich mulberry extract prevent hyperglycemia." (PMID 37241737, 2023). "Curcumin inhibits hyperglycemia-induced inflammatory damage in human RPECs through the ROS-PI3K/AKT/mTOR signaling pathway." (PMID 37978169, 2023). "EVs derived from hyperglycemia-induced activated platelets act on the mammalian target of rapamycin (mTOR) pathway in glomerular ECs to exacerbate glomerular endothelial damage and albumin leakage in urine, promoting the development of DN at an early stage." (PMID 37907962, 2023). "AEs reported in mTOR inhibitors plus endocrine studies include stomatitis, fatigue and asthenia, diarrhea, cough, pyrexia, and hyperglycemia." (PMID 37644396, 2023). "The serious toxicities of PI3K/AKT/mTOR inhibitors limit their clinical use and approval, including hyperglycemia, hyperlipidemia, bone marrow suppression, pneumonia, stomatitis, and hepatotoxicity." (PMID 38057772, 2023). "Future studies are needed to obtain a better understanding regarding the involvement of the mTOR pathway in bone resorption in hyperglycemia." (PMID 37298150, 2023). "Specifically, it is crucial to further investigate the mechanisms by which hyperglycemia disrupts the integration of extracellular and intracellular signals and how this dysregulation affects mTOR pathway activity." (PMID 37298150, 2023). "The molecular process behind bone pathogenesis in hyperglycemia has been extensively studied, with particular attention given to mTOR signaling in recent years." (PMID 37298150, 2023). "The aim of this study was to investigate the role mTOR plays in pulmonary vasculogenesis during fetal lung development under maternal hyperglycemia." (PMID 36927703, 2023). "The western blot analysis revealed significantly higher mTOR (p < 0.01) and p-mTOR (Ser2448) (p < 0.001) levels in the GDM fetal lungs than in the controls, indicating that maternal hyperglycemia stimulates the total mTOR signaling in fetal lungs." (PMID 36927703, 2023). "Several immunosuppressive agents (prednisone, calcineurin inhibitors and mTor antagonists) contribute to post-transplant hyperglycemia." (PMID 37759585, 2023). "This review summarizes key findings from basic and clinical studies regarding mTOR’s roles in regulating bone formation, bone resorption, inflammatory responses, and bone vascularity in hyperglycemia." (PMID 37298150, 2023). "The kinase, mammalian target of rapamycin (mTOR), resides at the interface between hyperglycemia and biochemical modifications." (PMID 36388931, 2022).
Hyperglycemia (continued). "This review addresses how hyperglycemia alters mTOR pathways during DR and provides useful tools for understanding normal retinal anatomy and the role of mTOR in tissue generation and in the pathophysiology of DR." (PMID 36388931, 2022). "One regulator of mesangial dysfunction in hyperglycaemia is mammalian target of rapamycin (mTOR) which plays a role in the occurrence and development of diabetic nephropathy." (PMID 35299891, 2022). "As for common safety concerns, CDK4/6 inhibitors and PI3K/AKT/mTOR inhibitors showed different profiles in hepatotoxicity, gastrointestinal (GI) toxicity, and hyperglycemia." (PMID 36091147, 2022). "Our results show that DI-10 reversed the effects of hyperglycemia in skeletal muscle by activating protein synthesis through the Akt/mTOR pathway and preventing protein degradation by downregulating Murf-1 and MAFbx through FoxO3." (PMID 35454154, 2022). "From these indications, mTOR inhibitors are known to induce dyslipidemia in 25–76% and hyperglycemia in 13–50% of patients." (PMID 35804402, 2022). "From the pathophysiological point of view, mTOR remains constantly activated because of persistent hyperglycemia." (PMID 35845058, 2022). "In the current work, mTOR contributes to DPN development in STZ receiving animals due to hyperglycemia-reduced AMPK activation or -enhanced TNF-α, which were formerly documented." (PMID 35767208, 2022). "Hyperglycemia can activate the AKT/mTOR/AMPK signaling pathway which is involved in tamoxifen resistance." (PMID 33718202, 2021). "The PI3K/AKT/mTOR pathway is an important oncogenic signaling pathway in BC that can be activated by hyperglycemia to promote the proliferation of malignant BC epithelial cells." (PMID 33718202, 2021). "Collectively, our study describes the mechanisms of neurodegeneration through the hyperglycemia/ mTOR/ autophagy/ apoptosis pathway." (PMID 33637094, 2021). "Determine the impact of the mTOR inhibitor, rapamycin, on the hyperglycemia-induced expression of vascular endothelial growth factor (VEGF) and the production of reactive oxygen species (ROS) in retinal cells." (PMID 33479328, 2021). "Metabolic effects of inhibiting mTOR with everolimus in patients include hyperglycemia, attributed to suppression of key glycolytic enzymes and the pentose phosphate pathway." (PMID 34731180, 2021). "In conclusion, the results of this study demonstrated that hyperglycemia inhibited AMPK/mTOR‐mediated autophagy induction, leading to enhanced NLRP3 inflammasome activation in KCs and increased TAA‐induced acute liver injury." (PMID 31625631, 2020). "Our findings demonstrated that hyperglycemia aggravated TAA‐induced acute liver injury by promoting liver‐resident macrophage NLRP3 inflammasome activation via inhibiting AMPK/mTOR‐mediated autophagy." (PMID 31625631, 2020). "Our results demonstrated that hyperglycemia induced NLRP3 inflammasome activation by inhibiting mTOR‐mediated autophagy in KCs in TAA‐induced acute liver injury." (PMID 31625631, 2020). "Akt paeoniflorin was shown to have anti-inflammatory and anti-hyperglycemia properties and has a potential ability to suppress mammalian target of rapamycin (mTOR) signaling." (PMID 33240030, 2020). "In conclusion, these results showed that hyperglycemia induced NLRP3 inflammasome activation by inhibiting AMPK/mTOR‐mediated autophagy activation in KCs in TAA‐induced acute liver injury." (PMID 31625631, 2020). "We also found that mitochondria in tubular epithelial cells were seriously injured and mitophagy was inhibited by acute hyperglycemia through AMPK/mTOR regulation." (PMID 33424763, 2020). "Patients treated with PI3K/AKT/mTOR pathway inhibitors developed hyperglycemia of grade 3–4 (6.7% vs. 0% of controls)." (PMID 32498358, 2020). "Hyperglycemia activates mTOR primarily through the phosphatidylinositol 3-kinase/Akt signaling pathway." (PMID 32455017, 2020).
Hyperglycemia (continued). "For example, in hyperglycemia, gold nanoparticles reduce inflammation and apoptosis through tuberin-mTOR/ NFκB pathway inhibition in macrophages." (PMID 31040851, 2019). "Inhibition of mTOR signaling using rapalogs, including rapamycin produces debilitating and serious side-effects such as rash, anemia, fatigue, hyperglycemia, decreased appetite, nausea, and diarrhea." (PMID 31194026, 2018). "Overactivation of mTOR resulted from prolonged exposure to hyperglycemia, which is a crucial factor in diabetic kidney injury." (PMID 30467302, 2018). "Hyperglycemia is a known class effect of agents targeting the PI3K/AKT/mTOR signaling pathway and was expected based on previous reports of other PI3K inhibitors and the first-in-human study of copanlisib." (PMID 27915408, 2017). "Glucose intolerance and hyperglycemia are common side effects of mTOR inhibitors used to treat cancer, due to their critical role in glucose homeostasis." (PMID 29137365, 2017). "Another mTOR inhibitor, temsirolimus, which is used intravenously to treat RCC, causes hyperglycemia in approximately 50% of patients." (PMID 28781589, 2017). "Hyperglycemia is an expected side effect of PI3K/AKT/mTOR pathway inhibition given the role of the pathway in regulating insulin signaling and glucose homeostasis." (PMID 26931343, 2016). "Although the clinical data are not sufficient, animal data suggest that the mechanisms responsible for hyperglycemia with mTOR inhibitors are likely due to the combination of impaired insulin secretion and insulin resistance." (PMID 27338360, 2016). "All patients who receive mTOR inhibitor therapy should be screened and regularly monitored for hyperlipidemia and hyperglycemia." (PMID 27287020, 2016). "Inhibition of the mTOR pathway provides clinical benefit to patients with mRCC, but the mechanism leads to certain class effects, including hyperglycemia and hyperlipidaemia." (PMID 27287020, 2016). "Other types of immunosuppressant agents also contribute to hyperglycemia including the calcineurin inhibitors (tacrolimus more than cyclosporine) and inhibitors of the mammalian target of rapamycin (mTOR), such as sirolimus." (PMID 25721247, 2015). "Metformin, an agent that controls hyperglycemia in DM, inhibits mTOR activity and promotes autophagy." (PMID 26064426, 2015). "Therefore, aside from some common adverse effects caused by PI3K/Akt/mTOR inhibitors, such as hyperglycemia, rash, asthenia and mucositis, there are other chronic adverse effects that might develop over a longer term and that might not be detected in initial clinical trials." (PMID 25334061, 2014). "Because hyperglycemia occurs along with hyperinsulinemia in obese type 2 diabetic patients, combined hyperinsulinemic and hyperglycemia would be expected to activate the mTOR pathway in obese and type 2 diabetic patients." (PMID 25126552, 2014). "The mTOR inhibitor rapamycin restores NO production by VMH GI neurons during hyperglycemia suggesting potential overlap in glucose and amino acid sensing pathways in these neurons." (PMID 25540613, 2014). "Early-phase clinical trials of agents targeting single points along the IGFR/PI3K/Akt/mTOR pathway reported only mild to moderate adverse events, including hyperglycemia, fatigue, skin rashes and gastrointestinal toxicities." (PMID 24387108, 2014). "In this study, expected known class-effect toxicities related to mTOR inhibitor therapy were observed, including anemia, hypertriglyceridemia, hyperglycemia, hypercholesterolemia, pulmonary events, and stomatitis." (PMID 23514360, 2013). "Expected known class-effect toxicities related to mTOR inhibitor therapy were observed, including anemia (64%), hypertriglyceridemia (55%), mouth ulceration (53%), hyperglycemia (52%), hypercholesterolemia (50%), and pulmonary events (31%)." (PMID 23514360, 2013). "The adverse event profile of mTOR includes hyperglycemia, hyperlipidemia, asthenia, hematological toxicity, pneumonitis, infections, and mucositis." (PMID 22978809, 2012).
Hyperglycemia (continued). "While maternal hyperglycemia is a key driver, evidence describes the role of dysregulated placental nutrient transport involving glucose, amino acids, and lipids mediated by signaling hubs like mTOR, IGF, and AMPK." (PMID 41710943, 2026). "Everolimus is an mTOR inhibitor that can be used in metastatic insulinoma due to its antiproliferative activity and desirable side effect of hyperglycaemia mediated through impaired peripheral glucose uptake, impaired beta cell insulin secretion and increased hepatic gluconeogenesis." (PMID 40697399, 2025). "Besides achieving relatively modest efficacy, single node PI3K/AKT/mTOR pathway inhibitors have been benighted by on-target/off-tumour toxicity, particularly hyperglycaemia." (PMID 40360883, 2025). "Besides this, hyperglycemia causes activation or overexpression of some protooncogenes, including hypoxia-inducible factor-1α (HIF1-α), AKT, mammalian target of rapamycin (mTOR), and c-myc." (PMID 39812937, 2025). "Therefore, under hyperglycemia, ROS activates mTOR, inhibits osteocyte autophagy, and induces osteocyte apoptosis, resulting in osteocyte dysfunction and diabetic osteoporosis." (PMID 41300463, 2025). "Conversely, fermented AS preparations may inactivate PI3K/Akt/mTOR signaling, activating podocyte autophagy to mitigate hyperglycemia-induced damage." (PMID 41155562, 2025). "Notably, a previous study showed that mTOR inhibitors are involved in adverse events such as hyperglycemia and hypercholesterolemia." (PMID 38835066, 2024). "Additionally, glucotoxicity caused by chronic hyperglycaemia and impaired branched-chain amino acid metabolism in patients with T2D further promotes MASH progression via mammalian target of rapamycin (mTOR) signalling." (PMID 39872125, 2024). "Hyperglycemia was likely induced by the mTOR inhibition in the setting of concomitant steroids." (PMID 38126764, 2024). "We observed minimal body weight loss in animals with this combination treatment, and no hyperglycemia which has been a previous on-target adverse effect of PI3K/mTOR pathway inhibitors that target mTORC245." (PMID 39025835, 2024). "Thus, understanding the detailed molecular process of mTOR-regulated bone metabolism in hyperglycemia is critical for developing strategies to combat diabetic bone diseases." (PMID 37298150, 2023). "Post-allograft transplant antirejection regimens (glucocorticoids, azathioprine, mycophenolate, calcineurin inhibitors and mTOR inhibitors) may trigger or aggravate hyperglycemia or hyperlipidemia." (PMID 37759585, 2023). "The detailed mechanism underlying the regulation of mTOR in osteoclastic activity in hyperglycemia is not well understood." (PMID 37298150, 2023). "Indeed, hyperglycemia further reduced MTOR methylation in diabetic HAECs and associated with enriched CTCF and Pol2B binding on the MTOR gene." (PMID 36633903, 2023). "Lesser degree of NETosis observed with hyperglycemic glucose concentration (i.e., 15 mM glucose, may indicate that hyperglycemia triggers NETosis independently of mTOR)." (PMID 36895726, 2023). "Overall, the present investigation demonstrated that calystegines possess important abilities to protect HuASCs against hyperglycaemia-induced cellular dysfunction, and it evidenced that the observed effects are associated to the promotion of PI3K/AKT/mTOR pathway." (PMID 35327652, 2022). "Other studies suggested that the impairment of autophagy in podocytes might be due to AGEs accumulation and subsequent mTOR hyperactivation, since pharmacological inhibition of mTOR could restore the autophagic flux even in the presence of hyperglycemia." (PMID 36686462, 2022). "Furthermore, our study clarified that Forsythiaside alleviated the detrimental effect of hyperglycemia on podocytes in diabetic podocytopathy possibly by inhibiting the mTOR signaling pathway." (PMID 36712665, 2022).